IL6 (interleukin 6)
Diseases named in the same sentence as IL6 in open-access papers (continued):
Sharing a sentence is not in itself a finding about the gene and the disease.
liver failure (continued). "IL-10, as an anti-inflammatory and cytoprotective cytokine, was only detected in peripheral blood, where higher levels in OLR indicated increased systemic inflammation and, together with IL-6 and MCP1, suggested an increased risk of postoperative liver failure." (PMID 41006707, 2025). "Furthermore, the combination of serum IL-6 with a cut-off point of 37 pg/mL, liver failure, hospital-acquired infection, and mechanical ventilator use showed excellent prognostic ability for predicting 28-day mortality." (PMID 39724169, 2024). "Among the validated associations total Bilirubin and length of ICU and IMC stay can be identified as hubs in the network with several validated associations to cytokines (IL-6, IL-8), lab values (INR) and critical patient-centered outcomes (complications, liver failure) (Appendix—Table A3)." (PMID 35927556, 2022). "The multivariate analysis confirmed both cytokines as independent predictors of liver failure [IL-6: HR 1.43 (1.09–1.88), p = 0.01; CXCL10: 1.5 (1–2.24), p = 0.05] and liver recipient survival [IL-6: HR 1.36 (1.06–1.75), p = 0.016; CXCL10: 1.45 (1–2.1), p = 0.052]." (PMID 33758270, 2021). "The hepatic levels of IL-6 and TNF-α in the HFD group were significantly elevated by 49.4% (p < 0.05) and 69.1% (p < 0.05), respectively, compared to those in the ND group, indicating that HFD caused a typical liver failure inflammatory response." (PMID 34829565, 2021). "Trends for a higher percentage of primary non-function as cause of liver failure, and a higher percentage of graft failure as cause of liver recipient death were evident, especially when the high IL-6/CXCL10 category was analysed." (PMID 33758270, 2021). "Serum IL-6 levels also influencethe degree of liver failure." (PMID 24976841, 2014). "HGF and IL-6 are important growth factor and cytokine of proliver regeneration after liver failure." (PMID 23251190, 2012). "In summary, low serum AHSG level and intestinal endotoxemia are critical pathological states in subjects of liver failure, while the peripheral blood mononuclear cells and inflammatory factors such as TNF-α and IL-6 are important immune targets in the pathological process of liver failure." (PMID 21747711, 2011). "Moreover, experimental models have shown that zinc-deficient mice with hepatic failure exhibit greater neuroinflammation, upregulation of proinflammatory cytokines (e.g., TNF-α, IL-6), and worse performance in spatial memory tests compared with zinc-replete controls." (PMID 40362419, 2025). "In addition, the number of HPCs in IL‐6‐deficient mice decreased, and in the absence of IL‐6 signaling, more liver failure with cell necrosis and impaired regeneration occurred." (PMID 31094067, 2019). "Thus, higher levels of TMAO and TNFa/IL6/IL1b levels could lead to a synergistic feedback loop in liver failure." (PMID 29844325, 2018). "Furthermore, in contrast to the CHB group, the HBV-ACLF group exhibited higher expressions of the inflammatory cytokines linked to liver failure, such as IFN-γ and IL-6, with trends resembling those of Gal-9, indicating that Gal-9 may be a biological marker for HBV-ACLF." (PMID 39333198, 2024). "The study also indicated that IL-6 concentration has the greatest significance, comparable to the Model of End-Stage Liver Disease (MELD) scale, in monitoring the degree of liver failure." (PMID 37834802, 2023). "The levels of cytokines, such as IL-10, IL-2, IL-4, IL-6, IFN-γ, and GM-CSF in PBC patients who developed liver failure, were significantly reduced, and the difference in IL-2 between the two groups was statistically significant (P=0.028)." (PMID 36159788, 2022). "IL-6 and EGF are key to liver regeneration, and mice defective in IL-6 were reported to develop post-hepatectomy liver failure." (PMID 32443494, 2020).
liver failure (continued). "It is worth mentioning that some inflammatory factors including IL-6, TNF-α, and CD8+T cells, which are induced by bacteria and endotoxins (lipopolysaccharide, LPS) from the gut, are significantly decreased after the BMSCs application in liver failure." (PMID 35122584, 2022). "Hepatic Tnf, interleukin (Il)-1β, and Il-6 mRNA were determined from these induced liver failure mice with or without GSK126 pre-treatment." (PMID 29789597, 2018). "In liver transplant recipients (liver failure), we observed negative values of WE ratios for Il-6, HGF, and TGF-β (−0.1, −0.5, and −0.2, respectively)." (PMID 26090463, 2015). "Indeed, in LPS/D-galactosamine (D-Gal)-induced liver failure, S1P levels were elevated, whilst the expression of SphK1, S1PR1, and S1PR3 was upregulated in the liver, and the levels of serum markers of liver failure, AST and ALT, and the serum cytokines TNF-α, IL-1, and IL-6 were increased." (PMID 39935473, 2025). "Studies have documented, in HE patients and rodent models with liver failure, the activation of microglia and hepatic macrophage, together with increases in pro-inflammatory factors, including tumor necrosis factor alpha (TNF-α), interleukin-1 beta (IL-1β), and interleukin-6 (IL-6)." (PMID 38725082, 2024). "The IL-6-promoted liver regeneration was determined in IL-6 knockout mice, as the deletion of il6 impaired the compensatory proliferation of hepatocytes by reducing the downstream STAT3 activation, thus promoting liver failure, which could be corrected by the treatment of IL-6." (PMID 38890694, 2024). "The negative elimination ratios of Il-6, HGF, and TGF-β indicate the prevalence of their intrahepatic synthesis in liver failure." (PMID 26090463, 2015). "In conclusion, the differences in Il-6, TNF-α, HGF, and TGF-β observed in liver donors between the portal and hepatic veins seem to result from their removal by healthy liver, which is absent in liver graft recipients with hepatic insufficiency." (PMID 26090463, 2015).
infarction (56 papers, 2010 to 2026). A localised pathological necrosis of tissue resulting from obstruction of the blood supply usually by a thrombus, an embolus, or vascular torsion. "On the other hand, literature data show that, in patients with STEMI, a higher IL-6 concentration is associated with a larger infarction area and, thus, a lower LVEF." (PMID 40428204, 2025). "High levels of IL-6 measured at all sampling points including 4 months were significantly associated with larger infarct size measured by CMR." (PMID 34933964, 2021). "In conclusion, our data indicate that IL-6 contributes to the development of infarction, in a closed-chest model of cardiac I/R that is associated with attenuated inflammation as compared to open-chest models." (PMID 26935770, 2016). "Surprisingly, both SN1 and SN2 treatments exerted comparable anti-inflammatory effects at day 1 post-MI, attenuating early post-infarction inflammation as reflected by the reduced expression of IL-1β and IL-6." (PMID 41301919, 2025). "There are also reports in the literature indicating that following IS, meningeal MCs secrete IL-6, which can significantly exacerbate cerebral edema, enlarge the infarction area, and increase the number of granulocytes and activated macrophages in the brain." (PMID 39253085, 2024). "On top of that, the infarction and myocardial injury also result in activation of the complement system and production of inflammatory cytokines including interleukin-1 (IL-1), interleukin-6 (IL-6), and tumor necrosis factor-α (TNF-α)." (PMID 35578329, 2022). "Serum IL-6 levels were identified as a strong predictor for the infarct size, with an area under the curve (AUC) of 0.685 (95% confidence interval of 0.593–0.768, p < 0.0002) and a cut-off value of >6.52 pg/mL, with 66.67% sensitivity and 19.7% specificity." (PMID 35268316, 2022). "In order to assess the potential of CSF IL-6 determinations as a diagnostic marker for DCI and infarction we performed ROC analyses." (PMID 33420113, 2021). "Among studied proteins, ST2 and IL–6 were unique in their correlation with early and final infarct size in both univariable and multivariable analyses." (PMID 33122738, 2020). "DSY decreased the infarction size, IL-6, CRP, TNF-α, and MAD, as well as enhanced SOD activities and glutathione." (PMID 30918578, 2019). "BIO treatment reduced serum levels of pro-inflammatory IL-6, which provides a potential mechanism to explain the increased numbers of M2 macrophages in the infarction zone." (PMID 27510556, 2016). "The beneficial effects of IL-6 deletion on infarction cannot be explained by modification of other inflammatory mediators, neutrophil influx or coagulation activation." (PMID 26935770, 2016). "When CD105+CD34- cells were administrated into the border area of the post-infarction scar they retain their ability to IL-6 secretion." (PMID 27415778, 2016). "Since HMGB1 has been shown to induce IL-6 we tested relations between infarction size, IL-6 and HMGB1." (PMID 20090932, 2010). "Moreover, hsCRP and IL-6 were significantly associated with NTproBNP, E/E’ as well as LVEF indicating a direct relation with infarct size and disease severity." (PMID 37407956, 2023). "Two hours of preconditioning reduced the IL-6 protein level in the brain after infarction." (PMID 34975719, 2021). "Moreover, peak Hsp70 levels 6 h after infarction correlated significantly with creatine kinase and cardiac troponin T levels, as well as with interleukin-6 (IL-6) and IL-8." (PMID 35083250, 2021). "The data suggested that BXT could decrease the infarction size, myeloperoxidase, interleukin-6 (IL-6), and levels of C-reactive protein (CRP) and enhance SOD activities and anti-inflammatory media such as interleukin-10 (IL-10)." (PMID 30918578, 2019). "Moreover, there was a significant correlation between IL-6 and infarction size in brain magnetic resonance imaging (MRI) scan (P < 0.001, r = 0.7)." (PMID 25295149, 2014).
infarction (continued). "The IL6/ADPN/HMGB1 loop between adipocytes and macrophages in the border zone contributes to different clinical outcomes post-infarction." (PMID 38601146, 2024). "Different outcome indexes were observed, and the most frequently used indicator was neurological severity score (in 19 studies); others included cerebral infarct size, cerebral edema volume, Bcl-2, Bax, VEGF, AKT, p-AKT, IL-6, SOD, and so on." (PMID 36637472, 2023). "In particular, IL-1β, IL-1Ra, IL-6, and MCP-1 showed 3-fold higher values in patients with extensive infarction; for patients who died, IL-1β was 3-fold greater and MCP-1 showed just less than a 3-fold difference." (PMID 33711020, 2021). "In summary, there already seems to be a surprisingly large body of data that describes elevated CSF (and serum) IL-6 levels in at least a significant number of patients, who later on develop DCI and DCI-related infarctions." (PMID 33923626, 2021). "Receiver operating characteristics (ROC) analysis and use of the Youden index showed that CSF IL-6 levels >44,500 pg/mL predicted DCI-related infarcts with a 94–98% specificity but only 46% sensitivity." (PMID 33923626, 2021). "Accordingly, in the current study we found that PTX3, IL-6 and hs-CRP arecorrelated with markers of myocardial necrosis during the first 12 hours ofmyocardial infarction." (PMID 32403934, 2020). "We monitored the mRNA levels of IL-1β, TNF-α, IL-6 and MCP-1 in border zone of left ventricular infarct by RT-PCR." (PMID 31164920, 2019). "In addition, up-regulation of serum miR-146b was strongly correlated with plasma CRP, infarction volume, and NIHSS scores, and also correlated with serum IL-6." (PMID 39001884, 2024). "Together, these data support a potential role for elevated CSF IL-6 levels as a biomarker for DCI with infarction rather than for DCI in general." (PMID 33420113, 2021). "Furthermore, the serum levels of proinflammatory cytokines, including IL-6 and TNF-α, were significantly higher in the large-infarction group compared to the control group." (PMID 33375339, 2020). "A significant direct correlation was also observed between increased levels of IL‐6 and NHISS and mRS values obtained at baseline, which is most likely to proceed evidence of infarction obtained through CT scan at ultimately 12 hr after admission to the emergency department." (PMID 32583980, 2020). "However, it has been found that knockout of IL-6 in the infarcted myocardium can be compensated by other family members, rendering the absence of IL-6 inconsequential to post-infarction myocardial function and remodeling." (PMID 40323498, 2025). "Thus, targeting the IL6/ADPN/HMGB1 loop may be a novel therapeutic approach for cardiac lymphatic regulation and reduction of cell senescence post-infarction." (PMID 38601146, 2024). "Significant IL-6 and uric acid production inboth the groups of CAD, HTN with and without T2DM when compared to healthy controls might be used for early men interventions ofmyocardial infarction in the future." (PMID 37701509, 2022). "However, other studies have reported that carriers of IL-6 gene knockdown showed no influence on infarct size, ventricular remodeling, left ventricular function, or mortality at prolonged follow-up after AMI induction in experimental animals." (PMID 31778438, 2019).
nephritis (56 papers, 2010 to 2026). Inflammation of renal tissue. "Although a few studies suggested that serum IL-6 might be associated with nephritis and central nervous system involvement, it is hard to perform the relevant pooled analyses due to the lack of sufficient data in the included studies." (PMID 33084768, 2020). "Similarly, IL-6-deficient MRLlpr/lpr mice showed greatly improved survival with significant amelioration of renal immunopathology, and in B6.Sle1.Yaa mice, IL-6 deficiency eliminated autoantibody production and nephritis." (PMID 26579125, 2015). "The increasing level of IL-6 could cause B cells to secret more antibodies and promote the development of nephritis." (PMID 20706659, 2010). "Another study found that miR-128-3p increased the expression of inflammatory cytokines such as TNF-α, IL-1β, and IL-6, whereas IL-1β is a key cytokine in kidney inflammation." (PMID 41440335, 2025). "In fact, neutralization of IL-6 and IL-6 receptor (IL-6R) reduced disease severity, while it has been highlighted that anti-IL-R6 or anti-IL-6 strategies increased the severity of nephritis in the study models." (PMID 40243751, 2025). "Our results show that DASA treatment led to the upregulation of pro-inflammatory cytokines, such as NF-κB, TNF-α, and IL-6 suggesting the development of kidney inflammation." (PMID 39744177, 2025). "A neutralizing monoclonal antibody to the IL-6 receptor preserved kidney function and structure of glomeruli in a mouse model of nephritis, indicating therapeutic potential for targeting IL-6 signaling alone in CKD." (PMID 37371758, 2023). "Several studies reported that blocking IL-6 with anti-IL-6 antibodies or knockout of IL-6 significantly improved survival and delayed nephritis, whereas mice with IL-6 over-expression developed mesangial proliferative glomerulonephritis." (PMID 37322353, 2023). "R428 administration reduced inflammatory cytokine (IL-6) production, T cell infiltration, and nephritis disease activity." (PMID 36578056, 2022). "GM can increase the inflammatory infiltration of macrophages and produce TNF-α, IL-6, and other inflammatory factors, which promote the development of kidney inflammation." (PMID 36296715, 2022). "Multiple linear regression analysis showed that there was still a linear relationship between IL-6 (P < 0.05) and nephritis after excluding age, gender and drug interference." (PMID 33882880, 2021). "While protein levels of the inflammatory cytokines were not measured in the renal tissues, we observed that 4-week EMP treatment reduced urinary markers of kidney inflammation, i.e., IL-6 and AGP." (PMID 31168342, 2019). "IL-6 is a pro-inflammatory cytokine that plays a pathological role in several types of nephritis." (PMID 40497974, 2025). "In our animal studies, mycophenolate and rapamycin, whether administered as monotherapy or combination therapy to NZBWF1/J mice with active nephritis, showed comparable efficacy in suppressing IL-6 expression in the kidney (unpublished data)." (PMID 35571122, 2022). "IL-6 plays a pathological role in GN and other forms of nephritis." (PMID 36578056, 2022). "IL-6 is upregulated in the kidneys and was crucial in the onset of nephritis in lupus mice." (PMID 34205600, 2021). "However, anti-IL-R6 or anti-IL-6 strategies increased the severity of murine anti-GBM nephritis, while selective inhibition of IL-6 trans-signaling by sgp130Fc did not." (PMID 34307414, 2021). "IL-6 functions via classical signaling and trans-signaling, and trans-signaling plays a central role in crescentic GN in a nephrotoxic serum-induced murine model of nephritis." (PMID 34425760, 2021). "Therefore, it will be more clinically helpful to evaluate the correlation between IL-6 and specific manifestations such as nephritis and central nervous system involvement." (PMID 33084768, 2020).